TRPC6 (transient receptor potential cation channel subfamily C member 6)
Diseases named in the same sentence as TRPC6 in open-access papers (continued):
Sharing a sentence is not in itself a finding about the gene and the disease.
breast carcinoma (continued). "The frequency of TRPC6 expression in breast cancer averaged 73.4% (36/49) of the cases studied." (PMID 18452628, 2008). "Using Western blotting, we found that the TRPC6 proteins were expressed in breast carcinoma." (PMID 18452628, 2008). "We can thus speculate that the entry of Ca2+ through TRPC6 channel may induce breast cancer cell proliferation in response to G protein-coupled receptor signalling." (PMID 18452628, 2008). "However, little is known about the expression pattern of TRPC6 or its possible role in the development of cancer, and breast cancer in particular." (PMID 18452628, 2008). "Our results point towards an aberrant expression of TRPC6 channels in breast cancer." (PMID 18452628, 2008). "Thus, in triple negative breast cancer cells, such as MDA-MB-231 cells, SOCE has been reported to be strongly dependent on STIM1 and Orai1, with TRPC6 playing a relevant role in the surface expression of Orai1, while in luminal breast cancer cells SOCE is mostly mediated by STIM1, STIM2, and Orai3." (PMID 33916304, 2021). "Furthermore, TRPC6 was of importance in regulating breast cancer MDA-MB-231 cell migration." (PMID 32138386, 2020). "Similarly, TRPC6 is also highly expressed in breast cancer cell lines compared to normal control." (PMID 32211326, 2020). "Moreover, several isoforms of TRPC channels, dependent on the cell type, have been implicated in the CaSR activation-induced Ca2+ entry, such as TRPC3 in salivary ductal cells, TRPC1 in MCF-7 breast cancer cells and keratinocytes, and TRPC6 in aortic smooth muscle cells and cardiac myocytes." (PMID 24905090, 2014). "Recently, there has been increased interest in TRP channels, which are overexpressed and dysregulated in various carcinomas, such as TRPC3 in ovarian cancer, TRPC6 in hepatocellular carcinoma, TRPM7 in breast cancer and TRPM8 in prostate cancer." (PMID 40813985, 2025). "TRPC1 has been implicated in breast cancer cell proliferation, whereas TRPC6, TRPM7, and TRPV6 have demonstrated their involvement in the regulation of breast cancer cell proliferation and migration." (PMID 39334351, 2024). "In breast cancer biopsy tissues, TRPC3 and TRPC6 proteins (determined by Western blotting) were upregulated compared to normal breast tissue." (PMID 37240443, 2023). "In breast cancer, the level of TRPC1 and TRPC6 expression was similar in the noninvasive and invasive areas, regardless of the ER status." (PMID 32887395, 2020). "In breast cancers, TRPC1 and TRPC6 are found to be highly expressed in human breast ductal adenocarcinoma compared to the adjacent non-tumor tissues, indicating the potential roles of these two TRPCs in modulation of breast tumor progression." (PMID 32211326, 2020). "In contrast to TRPC6, TRPV4 is positively regulated pronounced cell death through apoptosis, oncosis, or necrosis in breast cancer or melanoma cells." (PMID 31189890, 2019). "Breast cancer cells from the different subtypes undergo remodeling of the expression of specific molecular SOCE components, including Orai1, Orai3, TRPC1 and even TRPC6." (PMID 30558192, 2018). "We have recently reported that TRPC6 overexpression in MCF7 and MDA-MB-231 breast cancer cell lines is essential for full activation of SOCE, as well as cell proliferation, migration and invasion." (PMID 30558192, 2018). "In summary, we provide strong evidence for a role of TRPC6 as a new regulator of SOCE, cell proliferation, migration and invasion in breast cancer cells." (PMID 30223530, 2018). "Consistent with this, the expression of a variety of Ca2+ channels is up-regulated in breast cancer cell lines and cancerous tissue, including Orai1, Orai3 and different TRP channels, such as TRPC6, TRPV6 and TRPM8, among others." (PMID 30558192, 2018). "In breast cancer biopsy tissues, TRPC3 and TRPC6 were the predominant TRPC genes expressed with TRPC3 and TRPC6 being significantly up regulated compared to normal breast tissue." (PMID 19689790, 2009).
breast carcinoma (continued). "In the lowly metastatic breast cancer cell line MCF-7, TRPC6 was the chief TRPC gene expressed while in the highly metastatic breast cancer cell line MDA-MB-231 both TRPC3 and TRPC6 were the predominant TRPC genes expressed." (PMID 19689790, 2009). "TRPC6 is more highly expressed than other TRPC channels in human breast cancer MCF-7/MDA-MB-231 cell lines (regardless of breast cancer subtypes) and tissues, but TRPC3 is highly expressed only in the estrogen receptor-negative MDA-MB-231 cells and tissues." (PMID 33806911, 2021). "Orai3-mediated SOCE in ER+ breast cancer cells has been shown to be modulated by the TRP channel, TRPC6, as TRPC6 knockdown or transient expression of a dominant negative TRPC6 mutant resulted in attenuation of the plasma membrane expression of Orai3 and well as SOCE inhibition in MCF7 cells." (PMID 34768857, 2021). "Expression of the TRPC6dn significantly attenuated the interaction of TRPC6 with the Orai channels in MCF7 and MDA-MB-231 cells (p < 0.05; n = 4), thus suggesting that TRPC6 channel function is essential for its interaction with Orai3 in MCF7 and Orai1 in MDA-MB-231 breast cancer cells." (PMID 30223530, 2018). "Hyperforin a specific activator of TRPC6 produced a significant reduction in cell growth for the breast cancer cell lines, while the non-cancerous breast cell line was unaffected." (PMID 19689790, 2009). "High expression of TRPC6 was detected in tissue of breast cancer and small or negative expression was detected in normal tissue." (PMID 18452628, 2008). "Since TRPC6 protein over expression in breast cancer is not correlated with tumor grade, estrogen receptor expression or lymph node positive tumors, one could think that TRPC6 plays a role primarily in proliferation and not in metastasis." (PMID 24204345, 2013). "Moreover, TRPC6 is highly expressed in breast carcinoma and is not correlated with estrogen receptor expression, tumour grade, or LNM." (PMID 18452628, 2008). "Using RNAi-mediated TRPC6 silencing as well as overexpression of the pore-dead dominant-negative TRPC6 mutant we have found that TRPC6 plays a relevant role in the activation of store-operated Ca2+ entry in the breast cancer cell lines but not in non-tumoral breast cells." (PMID 30223530, 2018). "Hence, we have evaluated whether TRPC6 plays a role in the activation of SOCE in breast cancer cells by transfecting non-tumoral MCF10A and cancer MCF7 and MDA-MB-231 cells with shTRPC6 or shRNAcv, as control." (PMID 30223530, 2018). "Unlike TRPC1 and TRPC6, TRPC5 has been identified to mediate chemotherapeutic resistance in breast cancers." (PMID 32211326, 2020). "Altogether these findings indicate that TRPC6 plays a relevant role in the activation of SOCE in MCF7 and MDA-MB-231 breast cancer cells while this protein has not a detectable role in non-tumoral MCF10A cells." (PMID 30223530, 2018).
cardiac hypertrophy (33 papers, 2012 to 2025). "In the cardiovascular system, TRPC6 contributes to cardiac hypertrophy, vasoconstriction, and pulmonary arterial hypertension, and in the central nervous system, TRPC6 has been associated with neurodegenerative disorders, including Alzheimer’s disease." (PMID 41373637, 2025). "A study in mouse cardiomyocytes revealed that overexpression of TRPC6 causes spontaneous cardiac hypertrophy and remodeling." (PMID 32116757, 2020). "Studies performed on animal models showed there is an association between ventricular hypertrophy and increased expression of TRPC6 (transient receptor potential canonical 6) channels, whose expression is regulated by a wide range of redundant mechanisms." (PMID 30934737, 2019). "In contrast, in the heart upregulation of TRPC6 has been linked to the development of pathologic cardiac hypertrophy through activation of the calcineurin-NFAT pathway." (PMID 23171048, 2012). "WT mice subjected to HFD+L-NAME developed cardiac hypertrophy, diastolic dysfunction, and exercise intolerance, whereas TRPC6 KO mice, under the same conditions, maintained preserved diastolic function, exercise tolerance, and cardiac reserve." (PMID 41096654, 2025). "Treatment of TAC-operated mice with PPZ2 significantly improved LV dysfunctions and structural remodeling, such as myocardial hypertrophy and interstitial fibrosis, in a TRPC6-dependent manner." (PMID 36289215, 2022). "The indices of myocardial hypertrophy and fibrosis were positively associated with CaN/NFAT and TRPC6 IHC expression." (PMID 33924991, 2021). "TRPC6 channels are involved in development of cardiac hypertrophy and related calcineurin-nuclear factor of activated T cells (NFAT) signaling." (PMID 32116757, 2020). "Previous studies have demonstrated that cardiac hypertrophy upregulated TRPC6 and inhibition of TRPC6 suppressed agonist-induced hypertrophic responses." (PMID 30246030, 2018). "Soluble Klotho protects the heart via inhibition of the transient receptor potential cation channel 6 (TRPC6) gene whose overexpression leads to cardiac hypertrophy and remodeling." (PMID 28977159, 2017). "TRPC6 is induced in heart hypertrophy and inhibition of TRPC6 has been shown to suppress agonist-induced hypertrophic responses." (PMID 27096430, 2016). "Recently TRPC6 gene has shown crucial role in pathological cardiac hypertrophy and remodelling in response to stress." (PMID 23976973, 2013). "Transient receptor potential canonical channel type 6 (TRPC6), a non-selective cation channel that mediates Ca2+ influx, is expressed in the heart and implicated in pathological cardiac hypertrophy." (PMID 41096654, 2025). "Notably, αKlotho is organoprotective: It protects from stress-induced cardiac hypertrophy through suppression of transient receptor potential cation channel subfamily C member 6 (TRPC6) or from ischemia/reperfusion injury." (PMID 36967770, 2023). "In addition, α-Klotho inhibits TRPC6 heart channels and regulates myofibroblast activity to protect cardiac hypertrophy and remodeling." (PMID 35795366, 2022). "Cardioprotective properties of klotho have previously been attributed to its suppressive effects on reactive oxygen species, reducing the severity of indoxyl sulfate-induced hypertrophy, and inhibition of Trpc6 as demonstrated in an animal model of stress-induced cardiac hypertrophy." (PMID 34778257, 2021). "Klotho may also reduce proteinuria by blocking the transient receptor potential cation channel (TRPC6) in podocytes, and in the heart, Klotho attenuates stress-induced cardiac hypertrophy via inhibition of TRPC6." (PMID 32188018, 2020). "For instance, Klotho has been shown to reduce stress-induced cardiac hypertrophy by inhibiting cardiac TRPC6 channels in cardiomyocytes, as well as to stimulate TRPV5 receptors in the renal distal tubules, thus allowing the regulation of phosphate metabolism independently of calcium levels." (PMID 30934737, 2019).
cardiac hypertrophy (continued). "Similarly, the overexpression of TRPC6 in transgenic mice leaded to the development of cardiac hypertrophy and heart failure." (PMID 30881310, 2019). "A recently published study suggests that sialogangliosides in lipid rafts can act as membrane receptors for sKlotho and that particularly the KL1 domain is sufficient to inhibit raft-dependent PI3K signaling and TRPC6 function thereby protecting against stress-induced cardiac hypertrophy in mice." (PMID 29849175, 2018). "Finally, purified recombinant KL1 domain inhibits TRPC6 in cultured cells and protects against stress-induced cardiac hypertrophy in mice." (PMID 29250031, 2017). "Considering the role of TRPC3/6 heterotetramer channels in cardiac hypertrophy, TRPC6 protein signaling complex, including TRPC1 and TRPC3, may function as mechano-activated cation channels in the cardiovascular system." (PMID 28936433, 2017). "Thus, direct inhibition of TRPC6 could be an alternative strategy to effectively suppress pathological cardiac hypertrophy and failure induced by adverse mechanical stress." (PMID 32231588, 2020). "The overactivation of TRPC3 and TRPC6 channels, coupled with the CaN-NFAT signaling pathway, plays a crucial role in the development of myocardial hypertrophy by enhancing the Ca2+ influx and promoting pathological cardiac remodeling." (PMID 40498020, 2025). "This creates a positive feedback loop, where increases in the TRPC3 and TRPC6 expression further amplify the CaN-NFAT pathway and contribute to cardiac hypertrophy." (PMID 40498020, 2025). "There is evidence that other canonical subunits are involved in cardiac hypertrophy, most notably Ca2+ influx through TRPC1, TRPC3, and TRPC6 channels initiates the calcineurin-NFAT hypertrophy signalling pathway." (PMID 38672459, 2024). "Transient receptor potential cation channel subfamily C member 6 (TRPC6) has been correlated to cardiac pathologies, including MI, cardiac hypertrophy and fibrosis." (PMID 37955687, 2023). "In cardiac disease, TRPC6 is a positive regulator of calcineurin-NFAT signaling and plays a critical role in angiotensin II-induced cardiac hypertrophy." (PMID 32116757, 2020). "Using animal models of pressure overload-induced heart hypertrophy, different studies demonstrated that TRPC1, TRPC3, and TRPC6 are upregulated in heart." (PMID 30881310, 2019). "Thus, TRPC6 is an important mediator of cardiac hypertrophy and may be a therapeutic target." (PMID 29250031, 2017). "In vivo application of the technology to TRPC6 mRNA helps prevent cardiac hypertrophy in thoracic aortic constriction-treated mice without detectable off-target effects." (PMID 41094015, 2025). "In addition, TRPC6 transgenic mice also resulted in enhanced sensitivity to mechanical stress, with an increase in calcineurin–NFAT signaling, and severe cardiac hypertrophy and failure." (PMID 32231588, 2020). "Increased PKG activity is also reported to suppress Ca2+/calcineurin-dependent cardiac hypertrophy induced by agonist stimulation and pressure overload, and blockade of PKG phosphorylation by TRPC6 mutagenesis canceled the PKG-dependent anti-hypertrophic action." (PMID 28936433, 2017). "In addition, AngII-induced cardiac hypertrophy is mediated by both TRPC3 and TRPC6." (PMID 32079284, 2020). "Other researchers also convincingly demonstrated an involvement of TRPC3 and TRPC6 and transgenic mice expressing dominant-negative forms of TRPC3, TRPC6 and TRPC4, which will also inhibit TRPC1 heteromeric, but not homomeric, channels are almost completely protected from cardiac hypertrophy." (PMID 25268281, 2014). "Therefore, our research shows that inhibition of TRPC6 activity mediates the antihypertrophic effects of ANP/BNP and suggests that inhibition of TRPC6 may prevent pathological effects, providing insights into potential effective treatment strategies for myocardial hypertrophy and remodeling." (PMID 35722101, 2022).
diabetic nephropathy (33 papers, 2015 to 2025). "For instance, autosomal dominant FSGS caused by mutation of the TRPC6 cation channel, as well as other podocyte-related diseases, including diabetic kidney disease, lupus nephritis, transplant glomerulopathy, and hypertensive renal injury, are associated with abnormal Ca2+ levels." (PMID 39586895, 2024). "In a mouse model of diabetic kidney disease, TRPC6 mediates the activation of calprotease, leading to impaired autophagy in podocytes, secondary cell damage, proteinuria, and accelerating the progression of DKD." (PMID 41536046, 2025). "An up-regulation of TRPC6 channels has been reported in renal ischemia–reperfusion injury, where they seem to be involved in the podocyte response to renal damage and in diabetic nephropathy tissues and HK-2 cells cultured in high glucose concentrations." (PMID 41009007, 2025). "-Prevented the progression of diabetic nephropathy by modulating the crosstalk between TRPC6 and NADPH oxidases." (PMID 39768655, 2024). "It is known that TRPC6 expression is elevated in diabetic kidney disease, pulmonary hypertension, and cancer cells." (PMID 38397074, 2024). "In diabetic kidney disease, TRPC6 signaling in podocytes is overactive due to increased humoral factors such as Ang II and others, as well as increased ROS production via NOX." (PMID 36672207, 2023). "Based on these observations it was predicted that TRPC6 knockout or inhibition would ameliorate diabetic nephropathy (DN)." (PMID 36421724, 2022). "TRPC6 knockout has proven to be less effective at reducing diabetic nephropathy in mouse and rat models." (PMID 36421724, 2022). "The expression and activity of TRPC6 channels were elevated in various in vivo and in vitro diabetic nephropathy models." (PMID 33377622, 2021). "In diabetic nephropathy, TRPC6 is upregulated, suggesting a putative role of TRPC6 expression in the progression of diabetic nephropathy pathology." (PMID 33121167, 2020). "On the basis of these data, the authors suggested that TRPC6 inhibition had partial renoprotective effects in diabetic kidney disease." (PMID 31877991, 2019). "This study provides evidence that MYH9 downregulation in diabetic nephropathy induces podocyte dysfunction through the reorganization of the actin cytoskeleton, which is driven by TRPC6-mediated Ca2+ influx by NOX4-mediated ROS generation." (PMID 31118506, 2019). "Since these initial observations, enhanced expression of TRPC6 has been demonstrated in other kidney diseases including rodent models of diabetic nephropathy, nephrotoxic serum nephritis, rodent models of FSGS, and ureteral obstruction." (PMID 31877991, 2019). "The evidence of a role for TRPC6 hyperactivity in diabetic kidney disease is evolving." (PMID 36672207, 2023). "In diabetic nephropathy, excessive activation of TRPC6 channel activity plays an important role in podocyte apoptotic injury, and Wnt/β-catenin signaling pathway may be active in this process." (PMID 36277193, 2022). "We then describe studies using TRPC6 knockout mice and rats subjected to treatments that model human diseases, including nephrotic syndromes, diabetic nephropathy, autoimmune glomerulonephritis, and acute kidney injuries induced by renal ischemia and by obstruction of the urinary tract." (PMID 36421724, 2022). "Finally, and somewhat unexpectedly, the effects of TRPC6 knockout in diabetic kidney disease models in rodents have been disappointing." (PMID 36421724, 2022). "Inhibition of TRPC6 activation may also be a potential therapeutic strategy for diabetic nephropathy." (PMID 34866402, 2022). "NOX4 can increase podocyte TRPC6, inducing renal damage in diabetic kidney disease." (PMID 36297636, 2022). "Our findings suggest that treatment with liraglutide may prevent the progression of diabetic nephropathy by modulating the crosstalk between TRPC6 and NADPH oxidases." (PMID 34680477, 2021). "Because of this, TRPC6 or NOX4 could be a target to slow the development of diabetic kidney disease." (PMID 32872338, 2020).